TSPAN8 (tetraspanin 8)
Description:
Structural component of specialized membrane microdomains known as tetraspanin-enriched microdomains (TERMs), which act as platforms for receptor clustering and signaling. Participates thereby in diverse biological functions such as cell signal transduction, migration and protein trafficking. Promotes ADAM17-mediated TNF processing through recruitment of ADAM17 to tetraspanin-enriched micro-domains (TEMs). Forms a complex with RICTOR and integrin alpha3/ITGA3 to mediate mTORC2 activation and AKT1 phosphorylation leading to cell migration. Reduces apoptosis and autophagy induced by high glucose levels through forming a complex with mTOR and RICTOR. Contributes to the maintenance of intestinal epithelial barrier and plays a role in the regulation of intestine inflammation by switching interferon gamma receptor 1/IFNGR1 from clathrin-dependent to lipid raft-dependent endocytosis route to limit STAT1 activation magnitude and duration. Acts as a modulator of the endothelin axis by associating with endothelin converting enzyme ECE1 and regulating its activity of conversion of the endothelin-1 precursor to endothelin.
Synonyms: TM4SF3; CO-029
Tractability: Antibody: UniProt places it where antibodies can reach, with high confidence; UniProt predicts a signal peptide or a membrane-spanning region; its Gene Ontology location is reachable by antibodies, with medium confidence. PROTAC: its protein half-life has been measured.
Gene: Protein-coding gene on chromosome 12 (71,124,454 to 71,441,898, reverse strand). Ensembl gene ENSG00000127324.
Subcellular location: Cell membrane
Subcellular location (Human Protein Atlas): Vesicles
Gene Ontology:
Molecular function: protein binding; integrin binding
Biological process: negative regulation of blood coagulation
Cellular component: extracellular exosome; plasma membrane; cell surface; membrane
Genetic constraint (gnomAD): Loss-of-function variants: 18 observed, 29.27 expected, observed/expected ratio (o/e) 0.61, 90% interval 0.42 to 0.91. The upper end of that interval is the gene's LOEUF score, 0.91, which puts it in group 3 of 6, group 1 being the genes least tolerant of losing a copy. Missense variants: 241 observed, 254.55 expected, observed/expected ratio (o/e) 0.95, 90% interval 0.85 to 1.05. Synonymous variants: 84 observed, 85.11 expected, observed/expected ratio (o/e) 0.99, 90% interval 0.83 to 1.18.
Homologues: Orthologues: chimpanzee TSPAN8 (97% identical), macaque TSPAN8 (77% identical), dog TSPAN8 (74% identical), rat Tspan8 (70% identical), guinea pig TSPAN8 (70% identical), mouse Tspan8 (70% identical), rabbit TSPAN8 (65% identical), tropical clawed frog tspan8 (55% identical), pig TSPAN8 (50% identical). Paralogues in human: TSPAN9 (31% identical), CD81 (31% identical), CD82 (31% identical), CD9 (31% identical), TSPAN1 (31% identical), TSPAN4 (31% identical), TSPAN17 (30% identical), TSPAN5 (30% identical), TSPAN18 (30% identical), CD151 (30% identical), CD53 (27% identical), TSPAN11 (27% identical), and 20 more.
Diseases named in the same sentence as TSPAN8 in open-access papers:
TSPAN8 is named in the same sentence as 76 diseases in open-access papers, as found by Europe PMC text mining. Sharing a sentence is not in itself a finding about the gene and the disease. The quoted sentences say what the papers report.
colorectal cancer (30 papers, 2007 to 2025). A primary or metastatic malignant neoplasm that affects the colon or rectum. "The upregulation of TSPAN8 promotes cancer cell stemness, and a high expression of TSPAN8 is associated with a poor prognosis in breast cancer, colorectal cancer, lung adenocarcinoma." (PMID 35246069, 2022). "TSPAN8 is one of the tetraspanins that is positively correlated with colorectal cancer, with its high expression being linked to low chances of survival in this particular category of patients." (PMID 34830819, 2021). "In addition, elevated levels of tetraspanin 8 in blood serum may have diagnostic significance in the screening for colorectal cancer." (PMID 39031113, 2024). "However, whereas Tspan8 is functionally linked to cell migration in colorectal cancer and abrogates E‐cadherin function by collaborating with p120‐catenin and α2β1 integrin 14, in breast cancer Tspan8 is likely to act together with E‐cadherin, regulating cell–cell adhesion and proliferation." (PMID 30982971, 2019). "This therapy appears to be particularly effective in the case of tumors with higher tetraspanin 8 expression, such as colorectal cancer, glioblastoma, melanoma, hepatocellular carcinoma, ovarian cancer, and gastric cancer." (PMID 39031113, 2024). "For example, Tspan1 and Tspan8 are upregulated in pancreatic cancer and colorectal cancer, respectively, and promote tumor cell invasion, migration, and autophagy." (PMID 38649381, 2024). "Tetraspanin 8 is thought to facilitate colorectal cancer metastasis by promoting cell migration and interaction with adhesion proteins." (PMID 39031113, 2024). "A few of the Top 10 potential proteomic biomarkers revealed in our study have been previously identified as compounds associated with colorectal cancer’s response to RT, including CEACAM5, KHSRP, RALA, and TSPAN8." (PMID 38410100, 2024). "Conducted studies also indicate that tetraspanin 8 expression is increased in colorectal cancer compared with matched healthy control tissue." (PMID 39031113, 2024). "The second proposed mechanism of action of tetraspanin 8 in colorectal cancer is its positive effect on the expression of stem cell markers SOX2 and ALDH1." (PMID 39031113, 2024). "In colorectal cancer, Tspan8 augments the stemness of cancer cells via direct interaction with β-catenin and formation of a positive Tspan8/β-catenin expression regulatory loop." (PMID 38389703, 2024). "TSPAN8 has also been identified as an important modulator of motility in colorectal carcinoma cells." (PMID 38275818, 2024). "TSPAN8 is reported to be highly expressed in colorectal cancer, pancreatic cancer tissues and melanoma." (PMID 36941633, 2023). "In nasopharyngeal carcinoma, colorectal cancer, and melanoma, TSPAN8 also serves as a oncogenic factor to facilitate cell proliferation, invasion, and migration." (PMID 35246069, 2022). "TSPAN8 suppresses the motility of cells by regulating the tumor cell–matrix and cell to cell adhesion in colorectal cancer.At the same time, regulation by the E-cadherin/p120ctn complex has been found to be a promoter of invasion in colon cancer." (PMID 34830819, 2021). "In pancreatic and colorectal cancer cells, it appears that CD151 associates with TSPAN8 and integrin a6b4, the complex leading to PKC activation." (PMID 34830819, 2021). "Exosomes isolated from the peritoneal fluid of patients with colorectal cancer and from pancreatic adenocarcinoma cell cultures contains significant amounts of tetraspanin 8 (Tspan8), which promotes cancer metastasis and angiogenesis." (PMID 32823989, 2020). "It seems that Tspan8 mediates cell motility via collaboration with integrins α6β4 in pancreatic cancer 57, α3β1 in gliomas 58, and α2β1 in colorectal cancer." (PMID 30982971, 2019). "More recently, the presence of Tspan8 mRNA in the blood was shown to be a sensitive marker for colorectal cancer detection." (PMID 29946318, 2018).
colorectal cancer (continued). "Recently, a radiolabeled anti-Tspan8 mAb, labeled with lutetium-177 was effective against colorectal cancer in a xenograft model, showing a significantly reduced tumor growth." (PMID 29946318, 2018). "TSPAN8 mRNA has been also recently identified as a highly sensitive and specific blood biomarker for colorectal cancer (CRC) detection." (PMID 28423546, 2017). "Tetraspanin 8 (TSPAN8) overexpression is correlated with poor prognosis in human colorectal cancer (CRC)." (PMID 28423546, 2017). "TSPAN8 over-expression has been observed in gastrointestinal cancer, pancreatic cancer, colorectal cancer liver metastases, and intrahepatic spread of HCC." (PMID 27270327, 2016). "A CD44v6kd in human pancreatic and colorectal cancer (PaCa, CoCa) lines led to loss of CIC characteristics including downregulation of additional CIC markers, particularly Tspan8." (PMID 27419629, 2016). "In addition, Tspan8 overexpression not only facilitates the proliferation of colorectal cancer SW480 and SW620 cells but also promotes metastasis by facilitating the EMT process in an LSD1-dependent manner." (PMID 38389703, 2024). "Tspan8 can promote the growth and migration of colorectal cancer cells." (PMID 38649381, 2024). "Similarly, a positive regulatory loop between β-catenin and TSPAN8 regulated the expression of stemness genes for the maintenance of cancer stemness and the sphere-forming ability of colorectal cancer cells." (PMID 38275818, 2024). "Despite the fact that TSPAN8 has not been an available therapeutic target in HCC, there are several antibodies of TSPAN8 that may act as candidates for potential agents for colorectal cancer (CRC) and ovarian cancer." (PMID 34540692, 2021). "Furthermore, different intracellular locations of TSPAN8 in the cytoplasm and on the membrane were observed, as has already been described for colorectal cancer." (PMID 30982971, 2019). "High Tspan8 expression in colorectal cancer often indicate poor prognosis." (PMID 25761241, 2015). "Further, a mouse monoclonal antibody against Tspan8 could suppress colorectal cancer HT-29 xenograft in vivo growth in nude mice." (PMID 25761241, 2015). "Consequently, TSPAN8 inhibition, which has been successfully tested for ovarian and colorectal cancer with TSPAN8 inhibitory antibodies 16, 17, may be advantageous for therapy of TSPAN8 metastases." (PMID 30982971, 2019). "Based on a systematic large-scale meta-analysis on the blood samples, a panel of mRNAs of four genes—TSPAN8, LGALS4, COL1A2, and CEACAM6—were identified as putative markers of colorectal cancer." (PMID 38275818, 2024). "Other tetraspanin proteins including CD63, CD73, CD151, and Tspan8 have also been shown to modulate the EMT process and tumor progression in colorectal cancer, gastric cancer, melanoma, and renal cell carcinoma." (PMID 35280793, 2022). "In a rat model of colorectal cancer, a specific isoform of CD44, CD44v6, forms a complex with Claudin-7, a tetraspanin (TSPAN8/ CO-029) and EpCam." (PMID 28721385, 2016). "Also in colorectal cancer, LSD1 increases the expression of Tspan8 by interacting with the Tspan8 promoter and removing H3K9me2 from the promoter." (PMID 38389703, 2024). "TSPAN8 promotes the proliferation, migration and EMT process of colorectal cancer cells." (PMID 36941633, 2023). "Nevertheless, other tetraspanin proteins, such as TSPAN8 and CD9, may promote cancer self-renewal in colorectal cancer and glioblastoma, respectively." (PMID 36193887, 2022). "While its role in OA remains unclear, evidence from studies on colorectal cancer suggests that TSPAN8 modulates cell motility by linking epidermal growth factor receptor (EGFR) signaling to integrin/TLR-mediated pathways; EGFR silencing was found to enhance migration in TSPAN8-expressing cells." (PMID 41146237, 2025).
colorectal cancer (continued). "For example, the Isreco1 cell line derived from primary colorectal cancer (CRC) that does not express Tspan8 was compared with Is1-Co029, which was obtained by transduction to express Tspan8 at the same level as the two cell lines derived from metastases of the same patient." (PMID 30769765, 2019).
breast carcinoma (26 papers, 2019 to 2025). "In breast cancer, A high-dimensional flow cytometry single-cell analysis revealed a unique subset of senescence-like TSPAN8+ myCAFs that is associated with chemotherapy resistance and poor survival outcomes in several breast cancer patient cohorts." (PMID 40755775, 2025). "A recent study reported that BRCA2 mutation-associated breast cancers potentially originate from TSPAN8+ luminal progenitor cells." (PMID 38275818, 2024). "Recently, a subpopulation of TSPAN8+ myofibroblast-associated fibroblasts (myCAFs) has been identified as being associated with treatment resistance and poor survival rates in multiple breast cancer patient cohorts." (PMID 39769140, 2024). "Tspan8+ tumors developed many liver and spleen metastases in a syngeneic rat breast cancer model, but Tspan8 tumors had a much-reduced predisposition for metastasis, showing that Tspan8 plays a role in metastases." (PMID 36059497, 2022). "Similarly, Tspan8 expression in breast cancer cells was associated with increased levels of E-cadherin in EVs, probably as a consequence of the regulation of E-cadherin expression by Tspan8." (PMID 40135387, 2025). "TSPAN8, also known as CO-029 or TM4SF3, belongs to the tetraspanin family and has been reported to be associated with multiple cancer types, such as hepatocellular carcinoma, pancreatic adenocarcinoma, colon carcinoma, breast cancer." (PMID 34222025, 2021). "For instance, Tspan8 transfection in breast cancer cells was shown to enhance EV attachment to recipient cells and stimulate their migration." (PMID 40135387, 2025). "It has been demonstrated that increased expression of tetraspanin 8 in breast cancer stem cells promotes the expression of stem cell markers such as NANOG, OCT4, and ALDH1." (PMID 39031113, 2024). "For instance, TSPAN8 knockdown attenuated the effects of EGF on gastric cancer cell proliferation and invasion, while the suppression of endogenous EGF expression by KDM2A, a histone demethylase, decreased TSPAN8 expression in breast cancer cells." (PMID 38275818, 2024). "Tspan8 upregulation promotes breast cancer stemness and drug resistance.Tspan24 binds to integrin α6 and EGFR." (PMID 38649381, 2024). "A protein complex containing E-cadherin, p120-catenin and TSPAN8 has been identified to play an important role in cell motility and cancer metastasis in colon carcinoma and breast cancer." (PMID 38275818, 2024). "Tspan8 expression is upregulated in breast cancer stem cells, and upregulation of Tspan8 expression leads to increased drug resistance and stemness in tumor cells." (PMID 38649381, 2024). "Mechanistically, Tspan8 enhances breast cancer cell stemness by interacting with PTCH1, recruiting ATXN3 deubiquitinating enzymes to inhibit proteasome-mediated degradation of the SHH/PTCH1 complex, and activating the Hedgehog signaling pathway." (PMID 38649381, 2024). "Using breast cancer cells to obtain Tspan8-enriched small extracellular vesicles (SEVs), Tspan8 facilitated the binding of breast cancer cell-derived SEVs to target cells by enhancing the restriction of spreading and inducing restriction of fibroblasts." (PMID 38649381, 2024). "In breast carcinoma, Tspan8 overexpression promoted the stemness and drug resistance of breast cancer cells by facilitating the activation of the Sonic Hedgehog signaling pathway." (PMID 38389703, 2024). "Mechanistically, TSPAN8 was shown to promote cancer cell stemness in breast cancer through the activation of the sonic Hedgehog (SHH) signaling pathway, which led to the upregulation of stemness-related genes." (PMID 38275818, 2024).
breast carcinoma (continued). "Tspan8 is able to modulate the content and function of EVs in breast cancer, and Tspan8 mediates a several-fold increase in the number of EVs in cell culture and the circulation of tumor-bearing animals." (PMID 38649381, 2024). "The authors further revealed that blocking the translocation of TSPAN8 using a humanized monoclonal antibody hT8Ab4 can remarkably inhibit breast cancer growth in vitro and in vivo." (PMID 36941633, 2023). "Tspan8-enriched EVs exhibit stronger attachment to the target cells including breast cancer cells or fibroblast, by molecular adhesion." (PMID 36941633, 2023). "TSPAN8 mediated a several-fold increase in EV number in breast cancer cell culture and the circulation of tumour-bearing animals." (PMID 36941633, 2023). "Accordingly, the expression levels of TSPAN8, SHH, Patched1, and ATXN3 were positively correlated in human breast cancer specimens, and the high expression levels of TSPAN8 and ATXN3 correlated with poor outcome of the patients." (PMID 36768876, 2023). "In summary, it was established that Tspan8’s existence in primary breast cancer lesions and metastases, as well as its role as a regulator of cell behavior and EV release in breast cancer." (PMID 36059497, 2022). "TSPAN8 expression is correlated with a poor prognosis in breast cancer, renal cell carcinoma, and pancreatic cancer." (PMID 35877232, 2022). "The majority of initial breast cancer lesions and metastases to the brain, bone, lung, and liver contained Tspan8 protein." (PMID 36059497, 2022). "Our previous research revealed that the expression level of TSPAN8 is upregulated in breast cancer stem cells and correlates with chemotherapeutic resistance and poor prognosis." (PMID 34163029, 2021). "Our previous study demonstrated that TSPAN8 plays a key role in the regulation of breast cancer cell stemness via activation of sonic hedgehog signaling." (PMID 34163029, 2021). "Recently, it was reported the presence of Tetraspanin 8 (Tspan8) in breast primary tumor and metastases indicating its role as a regulator of cell behavior and EV release in breast cancer." (PMID 32443642, 2020). "TSPAN8 protein is present in the majority of human primary breast cancer lesions and metastases in different organs (the brain, bone, lung and liver)." (PMID 32138170, 2020). "Next, we tested co‐regulation of TSPAN8 and E‐cadherin in MDA‐MB‐361 human breast cancer cells expressing endogenous TSPAN8 and E‐cadherin." (PMID 30982971, 2019). "Our analyses of human breast cancer specimens revealed positive correlation among the expression levels of TSPAN8, PTCH1, SHH, and ATXN3." (PMID 31253779, 2019). "Accordingly, expression levels of TSPAN8, PTCH1, SHH, and ATXN3 are positively correlated in human breast cancer specimens, and high TSPAN8 and ATXN3 expression levels correlate with poor prognosis." (PMID 31253779, 2019). "Altogether, our findings show the presence of Tspan8 in breast cancer primary lesion and metastases and indicate its role as a regulator of cell behaviour and EV release in breast cancer." (PMID 30982971, 2019). "We found the protein level of TSPAN8, which is correlated with cancer progression, was strongly upregulated in the breast cancer spheres." (PMID 31253779, 2019). "Further investigation will be required to understand the molecular mechanisms of TSPAN8 up‐regulation in breast cancer cells." (PMID 30982971, 2019). "The microarray analysis of tumor samples of 90 breast cancer patients showed that TSPAN8 was highly expressed in TNBC and lowly expressed in luminal subtype." (PMID 31253779, 2019). "Tspan8 protein was present in the majority of human primary breast cancer lesions and metastases in the brain, bone, lung, and liver." (PMID 30982971, 2019). "On examining TSPAN8 expression in human breast cancer specimens, we observed great variations in the TSPAN8 expression levels within one specimen and between primary lesions and metastases originating from the same patient." (PMID 30982971, 2019).